GFI1 (growth factor independent 1 transcriptional repressor)
Description:
Transcription repressor essential for hematopoiesis. Functions in a cell-context and development-specific manner. Binds to 5'-TAAATCAC[AT]GCA-3' in the promoter region of a large number of genes. Component of several complexes, including the EHMT2-GFI1-HDAC1, AJUBA-GFI1-HDAC1 and RCOR-GFI-KDM1A-HDAC complexes, that suppress, via histone deacetylase (HDAC) recruitment, a number of genes implicated in multilineage blood cell development. Regulates neutrophil differentiation, promotes proliferation of lymphoid cells, and is required for granulocyte development. Inhibits SPI1 transcriptional activity at macrophage-specific genes, repressing macrophage differentiation of myeloid progenitor cells and promoting granulocyte commitment (By similarity). Mediates, together with U2AF1L4, the alternative splicing of CD45 and controls T-cell receptor signaling (By similarity). Regulates the endotoxin-mediated Toll-like receptor (TLR) inflammatory response by antagonizing RELA. Cooperates with CBFA2T2 to regulate ITGB1-dependent neurite growth. Controls cell-cycle progression by repressing CDKNIA/p21 transcription in response to TGFB1 via recruitment of GFI1 by ZBTB17 to the CDKNIA/p21 and CDKNIB promoters. Required for the maintenance of inner ear hair cells (By similarity). In addition to its role in transcription, acts as a substrate adapter for PRMT1 in the DNA damage response: facilitates the recognition of TP53BP1 and MRE11 substrates by PRMT1, promoting their methylation and the DNA damage response.
Synonyms: ZNF163; GFI1A; GFI-1; SCN2
Tractability: PROTAC: UniProt records ubiquitination sites on it; ubiquitination databases record sites on it.
Target class: Transcription factor
Gene: Protein-coding gene on chromosome 1 (92,472,360 to 92,486,925, reverse strand). Ensembl gene ENSG00000162676.
Subcellular location: Nucleus
Pathways (Reactome):
Developmental Biology: Transcriptional regulation of granulopoiesis
Gene Ontology:
Molecular function: DNA-binding transcription repressor activity, RNA polymerase II-specific; enzyme-substrate adaptor activity; protein binding; sequence-specific double-stranded DNA binding; transcription cis-regulatory region binding; DNA-binding transcription factor activity; RNA polymerase II cis-regulatory region sequence-specific DNA binding
Biological process: cellular response to lipopolysaccharide; DNA damage response; negative regulation of DNA-templated transcription; negative regulation of neuron projection development; negative regulation of transcription by RNA polymerase II; negative regulation of vitamin D biosynthetic process; positive regulation of interleukin-6-mediated signaling pathway; regulation of toll-like receptor signaling pathway; regulation of transcription by RNA polymerase II
Cellular component: nuclear body; nuclear matrix; nucleus; transcription repressor complex; transcription regulator complex
Genetic constraint (gnomAD): Loss-of-function variants: 15 observed, 32.31 expected, observed/expected ratio (o/e) 0.46, 90% interval 0.31 to 0.71. The upper end of that interval is the gene's LOEUF score, 0.71, which puts it in group 2 of 6, group 1 being the genes least tolerant of losing a copy. Missense variants: 462 observed, 505.68 expected, observed/expected ratio (o/e) 0.91, 90% interval 0.85 to 0.99. Synonymous variants: 231 observed, 224.2 expected, observed/expected ratio (o/e) 1.03, 90% interval 0.93 to 1.15.
Homologues: Orthologues: chimpanzee GFI1 (99% identical), macaque GFI1 (99% identical), dog GFI1 (93% identical), guinea pig GFI1 (93% identical), pig GFI1 (92% identical), rabbit GFI1 (92% identical), mouse Gfi1 (88% identical), rat Gfi1 (88% identical), tropical clawed frog gfi1 (67% identical), zebrafish gfi1ab (63% identical), Drosophila melanogaster sens (33% identical). Paralogues in human: GFI1B (46% identical), BCL6 (20% identical), ZBTB49 (20% identical), BCL6B (19% identical), ZBTB14 (18% identical), ZBTB46 (17% identical), ZBTB12 (16% identical), ZNF280B (16% identical), ZBTB21 (16% identical), ZNF280D (16% identical), FEZF2 (16% identical), PRDM13 (16% identical), and 16 more.
Diseases named in the same sentence as GFI1 in open-access papers:
GFI1 is named in the same sentence as 109 diseases in open-access papers, as found by Europe PMC text mining. Sharing a sentence is not in itself a finding about the gene and the disease. The quoted sentences say what the papers report.
leukemia (29 papers, 2013 to 2026). A malignant (clonal) hematologic disorder, involving hematopoietic stem cells and characterized by the presence of primitive or atypical myeloid or lymphoid cells in the bone marrow and the blood. "Overall, the individual contribution of other members of the CoREST complex in the oncogenic roles of GFI1 and other pathogenic factors in leukemia remains unclear." (PMID 40479062, 2025). "Here, we show that knockdown (KD) of Gfi1 in mice causes a fatal myeloproliferative disease (MPN) that could progress to leukemia after additional mutations." (PMID 29925903, 2019). "However, as we have discussed, patients from this cohort were not subcategorized based on karyotype, raising the possibility that GFI1 impacts on leukaemia in different ways according to the driver mutations." (PMID 28894287, 2017). "Interestingly, in human T-ALL patients with NOTCH1 mutations, or a transcriptional signature indicative of activated NOTCH1, GFI1 was highly expressed; while in mice, Gfi1 loss of function profoundly blocked Notch-initiated leukemia." (PMID 24068942, 2013). "A knockdown model of GFI1 accelerated the development of several leukemia models and led to the development of a fatal myeloproliferation, however not a complete knockout." (PMID 36969082, 2023). "For this purpose, we used MLL-rearranged leukemia cell models which are dependent on the physical interaction of LSD1 with GFI1 to maintain their proliferative, undifferentiated cellular state." (PMID 36171271, 2022). "Recent reports have shown that GFI1 acts as an oncoprotein in multiple malignancies, such as leukemia and several solid tumors, by promoting cell proliferation or suppressing the immune system." (PMID 35819844, 2022). "Complementing this observation, histone acetyltransferase inhibitor (HATi) treatment with CTK7a impeded leukaemia progression of GFI1-36N expressing leukemic cells." (PMID 35008835, 2021). "Reduced expression of GFI1 or presence of the GFI1-36N (serine replaced with asparagine) variant leads to epigenetic changes in human and murine AML blasts and accelerated the development of leukaemia in a murine model of human MDS and AML." (PMID 35008835, 2021). "Gfi1 is frequently mutated in patients with severe congenital neutropenia (SCN), leukemia, and lymphoma, suggesting a role as an oncogene in this tissue." (PMID 32630147, 2020). "Gfi1 was unmethylated in leukemia cell lines as was expected since it has been proposed as an oncogene in this tumor type." (PMID 32630147, 2020). "Originally, GFI1 was identified in a screen for factors promoting interleukin-2 independent growth of a leukemia T-cell line, demonstrating that GFI1 plays an important role in cell proliferation." (PMID 31649884, 2019). "To investigate the effect of increased expression of GFI1 in leukaemia development and to confirm our findings with the AML1-ETOtr model, we used an additional model." (PMID 29147018, 2017). "It has recently been shown that AML cells polarize macrophages towards a leukemia supporting state in a Growth factor independence-1 (GFI1) dependent manner." (PMID 28758974, 2017). "Thus, HMG20B is a critical component of the GFI1:LSD1 transcription repressor complex which contributes to leukemia cell differentiation block." (PMID 36171271, 2022). "Furthermore, histone acetyltransferase inhibitors (HATi), CTK7a treatment blocked leukaemia progression in healthy mice transplanted with GFI1-36N homo or heterozygous murine AML cells." (PMID 35008835, 2021). "Furthermore, we show that the growth factor independence 1 (GFI1) is a MYB-C/EBPβ-p300 target gene whose suppression by C/EBPβ-inhibitory STLs contributes to their ability to inhibit the proliferation of leukemia cells." (PMID 33958723, 2021).
leukemia (continued). "Growth factor independence-1 (Gfi1) is a transcriptional repressor with an important role in human malignancies, including leukemia, colorectal carcinoma, and lung cancer, but its role in prostate and breast cancer is unknown." (PMID 32630147, 2020). "However, KD, but also forced expression of GFI1/1B in human leukemia cell lines inhibited their growth and induced apoptosis." (PMID 31649884, 2019). "To investigate whether increased expression of GFI1 might impede leukaemia development, we first examined the effect of enforced GFI1 expression in vitro by using human haematopoietic stem and progenitor cells (HSPCs)." (PMID 29147018, 2017). "We finally aimed to investigate whether upregulation of GFI1 affects the ability of the leukemic cells to generate a transplantable leukaemia." (PMID 29147018, 2017). "We therefore investigated whether high GFI1 expression in the CN-AML FLT3-WT leukaemias corresponds to higher abundance of the FLT3-ITD molecular signature genes." (PMID 28894287, 2017). "We then investigated whether upregulated expression of GFI1 impedes the ability of cells to reconstitute leukaemia after transplantation." (PMID 29147018, 2017). "Thus, our study uncovers a novel epigenetic regulation mechanism in leukaemia involving the cooperation between TET1/GFI1 and polycomb factors." (PMID 27116251, 2016). "Conversely, in leukemias, ectopic over-expression of wild type or fusion Meis/Hox/Pbx proteins may displace Gfi1/1b repressive complexes from the promoters of such genes leading to their over-expression." (PMID 23308270, 2013). "Our family adds another 6 cases of confirmed GFI1 variant carriers (aged 20–75 years) and 2 likely carriers (over 71 years) without progression to myeloid malignancy, suggesting that the GFI1 variant alone does not confer a high risk of leukemia development." (PMID 32066420, 2020). "Super enhancer activation of LSD1’s direct targets such as GFI1 by LSD1 inhibition is an initial event occurring before gene upregulation and myeloid differentiation that is observed in leukemia." (PMID 36969082, 2023). "Functional assays demonstrated that HMG20B depletion induces leukemia cell differentiation and further revealed that HMG20B is required for the transcription repressor activity of GFI1 through stabilizing LSD1 on chromatin at GFI1 binding sites." (PMID 36171271, 2022). "Although progression to leukemia has not been described to date in the limited number of individuals carrying germline pathogenic GFI1 variants, it remains to be established whether molecular monitoring for acquired variants should be considered as part of a risk management scheme." (PMID 32066420, 2020). "Furthermore, when GFI1 is depleted, the myeloid differentiation induced by LSD1 inhibition is weakened, indicating that GFI1 is a target of LSD1 in leukemia." (PMID 36969082, 2023). "In leukemia cells, recruitment of LSD1 to chromatin genome-wide is overwhelmingly at sites of GFI1 binding and release of LSD1 from GFI1-occupied sites by disruption of protein:protein interaction is required for LSD1 inhibitor-induced leukemia cell differentiation." (PMID 36171271, 2022). "This role of GFI1 and GFI1B bears high significance for the ongoing effort to generate hematopoietic stem and progenitor cells de novo for the autologous treatment of blood disorders such as leukemia and lymphoma." (PMID 33193732, 2020). "Despite this accumulation of myeloid cells, Gfi1 deficiency alone, does not lead to the development of a myeloproliferative disease (MPN) or of an overt leukemia." (PMID 29925903, 2019).
leukemia (continued). "The curative effect that Gfi1 ablation has on the leukemia outweighs the negative effects that a deletion of Gfi1 will have, such as neutropenia, in particular since these will be transient." (PMID 23528269, 2013). "Finally, rs12067906 (p-value = 9.584×10-6) also maps in a DNAse hypersensitive region and onto two TFBS (corresponding to Gfi1 and HLF, both related to leukemia and several related pathologies)." (PMID 24289864, 2013). "On the contrary, transgenic mice for Gfi1 expression do not show an unusual incidence of leukemia." (PMID 32630147, 2020). "In this review we will discuss the molecular function of the GFI1/GFI1B CoREST complex, and describe how targeting of this complex forces myeloblasts to differentiate at the molecular and cellular level and how this could improve treatment of leukemia." (PMID 31649884, 2019). "The precise role of GFI‐1 in human HSPC is not known; therefore, I am evaluating the role of GFI‐1 in human HSPC and leukemia stem cells growth and differentiation." (PMID 29460395, 2018).
medulloblastoma (24 papers, 2015 to 2026). A malignant, invasive embryonal neoplasm arising from the cerebellum. "For medulloblastoma, we found SVs in noncoding regions that caused super-enhancer hijacking events of medulloblastoma driver genes (GFI1, GFI1B, and PRDM6)." (PMID 39322849, 2024). "LSD1 inhibitors such as GSK-LSD1 and ORY-1001 were shown to be effective for GFI1-activated medulloblastoma." (PMID 39322849, 2024). "In the application study of pediatric patients with medulloblastoma, we showed that various types of SVs caused neo-TAD formation of the same GFI1 families." (PMID 39322849, 2024). "In particular, GFI1/GFI1B overexpression was found to be a present in 15–20% of group 3 medulloblastoma and to play a significant role at the different stages of tumorigenesis." (PMID 37568705, 2023). "Two recent studies reported that GFI1 has been shown to favor the survival of myeloid cells in myeloproliferative disease and tumor maintenance in medulloblastoma." (PMID 36672361, 2023). "The interaction between LSD1 and growth factor independent 1 (GFI1) was shown in GFI1-driven medulloblastoma." (PMID 34066495, 2021). "Here we show that medulloblastomas driven by the transcription factor Gfi1 are exquisitely dependent on the enzyme lysine demethylase 1 (Kdm1a/Lsd1)." (PMID 30659187, 2019). "For instance, the analysis of medulloblastoma genome sequencing data revealed that juxtapositioning of enhancers to neighboring genes leads to increased expression of oncogenes such as GFI1 or GFI1b in sub-groups of medulloblastoma cases." (PMID 31555592, 2019). "In this regard, it is notable that GFI1 activity is not limited to hematopoietic tumours but also includes, among others, neuroendocrine lung carcinomas and certain aggressive subtypes of medulloblastoma." (PMID 31225488, 2018). "In fact, abnormal activation of GFI1B and GFI1 has been related to human medulloblastoma and is also likely to be relevant in blood malignancies." (PMID 28401061, 2017). "Other structural rearrangements place an enhancer near novel oncogenes, such as GFI1 and GFI1b in subtypes of medulloblastoma." (PMID 28333948, 2017). "In the G4 medulloblastomas, SVs affecting GFI1 and GFI1B and the recurrent tandem duplication of SNCAIP are known to cause overexpression of GFI1, GFI1B and PRDM6, respectively, by putting them under the control of super-enhancer regions (termed enhancer hijacking, EH)." (PMID 37576901, 2023). "In addition, it was suggested that LSD1 inhibitors have promising anti-proliferative effects against GFI1/GFI1B-driven group 3/4 medulloblastomas." (PMID 37568705, 2023). "Furthermore, our observation is in line with a recent study showing that Gfi1 overexpression contributes to enhanced tumorigenesis in medulloblastoma and small cell lung cancer." (PMID 30286780, 2018). "Unlike blood malignancies, GFI1B and GFI1 activation has been associated with solid tumors, in particular medulloblastoma." (PMID 28401061, 2017). "The oncogenic effect of mutations in the fusion genes such as ARID1A, PVT1, GFI1, MYCN, DNMT1, and TET3 has been identified in various tumors including medulloblastomas to regulate tumorigenesis, suggesting that the predicted inframe fusion proteins may possess oncogenic potential." (PMID 33681213, 2021). "Conversely, the elevated expression of GFI1 could explain chemo- or radio-resistance of lymphoid leukemia or lymphoma, as we observed here and have implications for treatment response in other tumor types that overexpress GFI1, including medulloblastomas and neuroendocrine lung carcinomas." (PMID 29651020, 2018). "In fact, local enhancer hijacking of GFI1 and distal enhancer hijacking of GFI1B drive medulloblastoma growth, either by cooperating with MYC to drive group 3 tumors or with other drivers to promote group 4 medulloblastoma development." (PMID 37568705, 2023).
medulloblastoma (continued). "It has been shown previously that Growth Factor Independent Protein 1 (GFI1) and GFI1B are transactivated by enhancers in group 4 medulloblastoma and form a complex with LSD1 and CoREST that promotes tumour growth." (PMID 35379950, 2022). "In this study, the authors show, using a mouse model of medulloblastoma, that Gfi1 promotes tumor growth by recruiting Lsd1, that this interaction inhibits genes involved in neuronal differentiation, and that Lsd1 may be a therapeutic target in Gfi1-activated tumors." (PMID 30659187, 2019). "These include combination therapy with PI3K pathway inhibitors (BKM-120) and histone deacetylase inhibitors (LBH-589) for MYC-driven group 3 medulloblastoma, targeting LSD1 in MB with GFI1/GFI1B over-activation, CDK inhibitors, and cell cycle checkpoint inhibitors." (PMID 40229260, 2025). "While mice overexpressing the gene combinations GFI1 + c-MYC (GM) and OTX2 + c-MYC (OM) induced brain tumors, only the latter combination developed medulloblastoma clustered with Group 3 subtype, highlighting the role of OTX2 and c-MYC as the medulloblastoma driver genes." (PMID 36831595, 2023). "While GFI1 and GFI1B overexpressing tumours show high LSD1 activity that could be blocked using specific chemical inhibitors, our findings show that inhibition of LSD1 increases stemness, raising caution over the use of LSD1 inhibitors in the treatment of specific subtypes of medulloblastoma." (PMID 35379950, 2022). "The RNAseq results also indicate that GFI1 was not highly expressed and GFI1B transcripts were not present at all, indicating that GFI1 and GFI1B were not the MYC-cooperating genes in this medulloblastoma." (PMID 26380221, 2015). "In addition to the BRCA2 6174delT, the medulloblastoma cells had amplification of MYC, deletion at Xp11.2, and isochromosome 17, but no structural variations or overexpression of GFI1 or GFI1B." (PMID 26380221, 2015).